ADPRH (ADP-ribosylarginine hydrolase)
Description:
Specifically acts as an arginine mono-ADP-ribosylhydrolase by mediating the removal of mono-ADP-ribose attached to arginine residues on proteins.
Synonyms: hARH1; ARH1
Tractability: Small molecule: a structure with a bound ligand is known. PROTAC: its protein half-life has been measured.
Gene: Protein-coding gene on chromosome 3 (119,579,268 to 119,590,165, forward strand). Ensembl gene ENSG00000144843.
Subcellular location (Human Protein Atlas): Nuclear membrane; Nucleoplasm
Gene Ontology:
Molecular function: ADP-ribosylarginine hydrolase activity; magnesium ion binding; potassium ion binding; protein binding
Biological process: protein de-ADP-ribosylation; protein modification process
Cellular component: extracellular region
Genetic constraint (gnomAD): Loss-of-function variants: 28 observed, 32.95 expected, observed/expected ratio (o/e) 0.85, 90% interval 0.63 to 1.16. The upper end of that interval is the gene's LOEUF score, 1.16, which puts it in group 5 of 6, group 1 being the genes least tolerant of losing a copy. Missense variants: 419 observed, 468.02 expected, observed/expected ratio (o/e) 0.9, 90% interval 0.83 to 0.97. Synonymous variants: 161 observed, 175.12 expected, observed/expected ratio (o/e) 0.92, 90% interval 0.81 to 1.05.
Homologues: Orthologues: chimpanzee ADPRH (99% identical), macaque ADPRH (98% identical), dog ADPRH (89% identical), pig ADPRH (87% identical), rabbit ADPRH (87% identical), guinea pig ADPRH (85% identical), rat Adprh (83% identical), mouse Adprh (82% identical), tropical clawed frog adprh (66% identical), zebrafish adprh (52% identical). Paralogues in human: ADPRHL1 (45% identical).
Diseases named in the same sentence as ADPRH in open-access papers:
ADPRH is named in the same sentence as 9 diseases in open-access papers, as found by Europe PMC text mining. Sharing a sentence is not in itself a finding about the gene and the disease. The quoted sentences say what the papers report.
glioma (3 papers, 2021 to 2022). A benign or malignant brain and spinal cord tumor that arises from glial cells (astrocytes, oligodendrocytes, ependymal cells). "ADPRH expression is tightly linked to tumor immune infiltrating cells (TIICs), and its high expression is associated with poor prognosis in glioma." (PMID 36497164, 2022). "Interestingly, not much is known about the functions of OTUD1, TCHH, ADPRH, PLBD1, and QPCT in glioma, which need further research in future." (PMID 36389681, 2022).
lymphoma (2 papers, 2021). A malignant (clonal) proliferation of B- lymphocytes or T- lymphocytes which involves the lymph nodes, bone marrow and/or extranodal sites. "Recent research shows that ADPRH plays a key role in the formation of lung adenocarcinoma and lymphoma 29 and involves in regulation of lymphocytes activation in lung and colorectal cancers." (PMID 33854592, 2021). "Of the 579 overrepresented proteins, six proteins were found in at least 20-fold higher abundance in lymphoma patients (NUCKS1, SLC14A1, GPALPP1, ADPRH, CD72, PRDM15)." (PMID 33562532, 2021).
colorectal cancer (1 paper, 2021). A primary or metastatic malignant neoplasm that affects the colon or rectum. "Meanwhile, recent research demonstrates ADPRH expression is upregulated in regulatory T lymphocytes (Treg) in colorectal cancer (CRC) and non-small cell lung cancer (NSCLC) by RNA sequencing and single-cell PCR and tend to be associated with lymphocytes activation." (PMID 33854592, 2021).
low grade glioma (1 paper, 2021). A grade I or grade II glioma arising from the central nervous system. "However, the association of ADPRH with low grade glioma (LGG) remains unclear." (PMID 33854592, 2021).
Obesity (1 paper, 2022). Accumulation of substantial excess body fat. "Again, 3 upregulated genes ADPRH, PADI2, and QKI are shared in T2D, obesity, and CVD." (PMID 36035865, 2022).
tumor (3 papers, 2021 to 2022). "After the correlation adjustment by purity, we discovered that the ADPRH expression was correlated with most of the gene markers of immune cells, in particular, strongly and positively with the markers of monocytes, tumor-associated macrophages (TAMs), M1 and M2 macrophages." (PMID 33854592, 2021). "By TIMER and ESTIMATE databases, we identified ADPRH expression had strong correlation with tumor immune infiltrating cells (TIICs)." (PMID 33854592, 2021). "Our cohort containing 18 LGG samples and 10 non-tumor brain samples further validated ADPRH was expression-upregulated in LGG tissues." (PMID 33854592, 2021). "Here, we analyzed expression level of ADPRH in LGG samples in transcriptomics and proteomics, calculated the prognostic value of ADPRH expression, and identified the correlative degree of ADPRH expression with tumor immune microenvironment (TIM) in LGG patients." (PMID 33854592, 2021). "Additionally, ADPRH may modulate anti-tumor immune response and promote the proliferation and progression of LGG." (PMID 33854592, 2021). "The expression level of ADPRH in LGG and non-tumor samples were first analyzed using the GEPIA database, revealing that the ADPRH was overexpressed in LGG samples in comparison to the normal brain tissues." (PMID 33854592, 2021). "The natural protein target of ADPRH has not been fully elucidated, and while mice lacking ADPRH are viable, evidence obtained from this knockout indicates that ADPRH acts as an important tumor suppressor." (PMID 34512719, 2021).
cancer (2 papers, 2019 to 2021). A tumor composed of atypical neoplastic, often pleomorphic cells that invade other tissues. "Of note, ADPRH had significantly higher expression levels in the lower-TMB subtype of 14 cancer types." (PMID 30634925, 2019). "We found that seven genes (ADPRH, IL1R1, KSR1, SOCS2, JAK1, NFAT5, and SSH1) were more highly expressed in the lower-TMB subtype than in the higher-TMB subtype of more than 10 cancer types." (PMID 30634925, 2019).
ADPRH also shares sentences with these, for which no sentence is quoted: cognitive decline (1 paper); lung adenocarcinoma (1).